ROCK1 (Rho associated coiled-coil containing protein kinase 1)
Diseases named in the same sentence as ROCK1 in open-access papers (continued):
Sharing a sentence is not in itself a finding about the gene and the disease.
tumor (continued). "ROCK1, a protein serine/threonine kinase, was reported to function as a key modulator of cell motility, tumor cell invasion, and actin cytoskeleton organization." (PMID 33390846, 2021). "Collectively, these sets of comprehensive investigations collective support higher tumor breakdown and higher anti‐tumor immune function of DR5 agonists when given in combination of ROCK1 inhibitors or PD‐L1 function inhibiting antibodies." (PMID 33587338, 2021). "When DR5‐treated tumor cells and jurkat co‐culture reporter assays were evaluated in the presence of ROCK1 inhibitors, luciferase activity was significantly enhanced in lieu with loss of surface PD‐L1." (PMID 33587338, 2021). "The DR5 agonist stimulated caspase‐8 signaling not only activates ROCK1 but also undermines proteasome function, both of which contributes to increased PD‐L1 stability on tumor cell surface." (PMID 33587338, 2021). "Inhibition of ROCK1 with the ROCK1 specific inhibitor (ROCK1i) Y-27632 or shRNA transfection reversed the effects of TEM8 on tumor cell VM, suggesting that ROCK1 was involved in the function of TEM8." (PMID 34285210, 2021). "A fine balance between the level of injury amplification that can be tolerated and the benefits from long-term tumour suppression has likely been achieved through evolution, including a role for ROCK1 cleavage to limit the extent of sterile inflammation." (PMID 33871359, 2021). "Previous studies implied that the miR-335/ROCK1 axis played diverse roles in the regulation of tumor initiation, progression, and relapse." (PMID 32219065, 2020). "Although the roles of miR-148b in regulation of tumor repression have been widely studied, only a few studies suggested ROCK1 and BRG1 as molecular targets related to EMT regulation." (PMID 32252322, 2020). "Mechanistically, we find that WNT11-FZD7-DAAM1 activates Rho-ROCK1/2-Myosin II and plays a crucial role in regulating tumour-initiating potential, local invasion and distant metastasis formation." (PMID 33082334, 2020). "Among of these members, RhoA has been lucubrated with its downstream target, Rho-associated coiled-coil kinase 1 (ROCK1) and researches have elucidated RhoA/ROCK1 pathway are related to EMT process and tumor metastasis." (PMID 32546278, 2020). "WNT11-FZD7-DAAM1 activates Rho-ROCK1/2-Myosin II to control tumour-initiating potential, local invasion and distant metastasis formation." (PMID 33082334, 2020). "We have shown that the ROCK1/2-Myosin II amoeboid phenotype sustained by FZD7-DAAM1 signalling supports tumour formation and dissemination." (PMID 33082334, 2020). "The tumor-suppressive effects of ROCK1 knockdown have been observed in many different types of cancers." (PMID 32554853, 2020). "Our data confirm that ROCK1/2-Myosin II activity is not only important for tumour formation and invasion but also for early colonization and later metastatic growth." (PMID 33082334, 2020). "ROCK1, its target, is one of the key players of actin cytoskeleton reorganization, which promotes tumor cell invasion through affecting the RhoA/ROCK1 signaling pathway." (PMID 33240194, 2020). "Accumulating evidence supports that ROCK1 acts as an oncogene and participates in tumor development and progression." (PMID 33168781, 2020). "Majority of previous literature about ROCK1 is about its role in tumorigenesis; for example, one previous research showed that a high level of ROCK1 expression leads to poor tumour differentiation and reduced survival." (PMID 32776418, 2020). "ROCK1 up regulation was associated with androgen receptor (AR) expression, TMPRSS2:ERG fusion, genomic deletions of the PTEN tumor suppressor, as well as recurrent deletions at chromosomes 3p, 5q, 6q." (PMID 31557128, 2019). "In addtion, ROCK1 can regulate tumor cell migration and invasion partially based on its role in regulating actin cytoskeleton." (PMID 31638991, 2019).
tumor (continued). "Up-regulation of ROCK1 and TPR and down-regulation of ALDH4A1 and CLCA2 are positively associated with the processes of migration, metastasis, and invasion of tumor cells and negatively associated with proliferation." (PMID 31438847, 2019). "These factors have been showed to be involved in chemotaxis (CXCR485) and locomotion (ROCK1/2, Acta2, Pak-1, Rac1, and RhoA28) of stromal cells to help migration of these cells to tumor niches." (PMID 31391540, 2019). "Knockout studies of ROCK1 and ROCK2 have shown that ROCKs are essential for cell cycle progression and tumorigenesis, but in order to achieve efficient tumor growth inhibition, it is preferable to target both ROCK1 and ROCK2 to avoid redundancy." (PMID 31888022, 2019). "And we also found that ROCK1 has significant higher expression in LUAD samples after analysing from TCGA unpaired 488 LUAD tumour and 57 adjacent normal tissues." (PMID 31483565, 2019). "Like flavonoid molecules, another ATF6 inhibitor melatonin modulates important kinases FAK, SRC and ROCK1 involved in tumor migration." (PMID 31064137, 2019). "Together, these results indicate that hirsutine effectively inhibits tumor growth in an A549 xenograft mouse model through ROCK1/PTEN/PI3K/Akt signaling-mediated GSK3β dephosphorylation and apoptosis." (PMID 29789524, 2018). "Results demonstrated that LOC441178 expression was negatively correlated with the ROCK1 level in the tumor tissues." (PMID 30364063, 2018). "Our in vivo study also showed that hirsutine effectively inhibits tumor growth in a A549 xenograft mouse model through ROCK1/PTEN/PI3K/Akt signaling-mediated GSK3β dephosphorylation and apoptosis." (PMID 29789524, 2018). "Western blot analysis conducted on excised tumor tissue from treated animals revealed that treatment with hirsutine resulted in cleavage/activation of ROCK1, activation of PTEN, inactivation of PI3K, Akt and dephosphorylation of GSK3β." (PMID 29789524, 2018). "This analysis revealed that ROCK1 was highly expressed in the majority of our tumor tissue samples, both in the tumor epithelial cells and in the surrounding stromal cells." (PMID 28841710, 2017). "Consistent with prior reports, our study shows that ROCK1 is important for not only migratory movement of tumor cells, but also ECM deposition in CAFs." (PMID 28841710, 2017). "In conclusion, our study demonstrated that miR-199a/b-5p acted as a tumor suppressor by post-transcriptionally suppressing ROCK1 that resulted in diminished ROCK1/MLC and PI3K/AKT signaling, thereby inhibiting HCC metastasis." (PMID 28978024, 2017). "Recently, the RhoA/ROCK1 signaling pathway has received considerable attention for its involvement in tumor formation and progression." (PMID 28184030, 2017). "It was shown that inhibition of both ROCK isoforms caused severe proliferation defects and loss of both ROCK1 and ROCK2 blocked tumor formation in mice." (PMID 28670628, 2017). "Even further, we detected MALAT1, miR-144-3p and ROCK1/ROCK2 expression in the formatted subcutaneous tumor nude mice specimens." (PMID 28938647, 2017). "The scrambled control and ROCK1 shRNA xenograft tumor-bearing mice were largely ulcerated and openly hemorrhaging on the primary lesion, however ROCK2 shRNA xenograft tumors exhibited no significant dermatological ulcerations." (PMID 28709411, 2017). "It was notable that downstream of PPP1CC and ROCK1 was MYL9, which was a famous hallmark tumor gene." (PMID 27634882, 2016).
tumor (continued). "There are several reports to illustrate the decrease in tumor suppressive microRNAs which directly regulate expression of ROCK1 and ROCK2 in other type of cancers." (PMID 27203208, 2016). "The inhibition of either the expression or the activity of Rac1, Pak1 or Rock1 leads to the suppression of tumor cell growth, invasion and metastasis." (PMID 26871290, 2016). "In tumor cells, ROCK1 and ROCK2 have recently been reported to have functional differences in regulating adhesion, migration, proliferation, and gene expression, but the underlying mechanisms are not fully understood." (PMID 26725045, 2016). "Deletion of Rock1 appears to increase tumor burden in the NSCLC model, whereas deletion of Rock2 leads to decreased tumor onset and survival in the melanoma model." (PMID 26765561, 2016). "The ROCK1 and 2 double-null cells, however, are unable to form a tumor as they are defective in cell proliferation and senesce." (PMID 26765561, 2016). "Cross-breeding the conditional mice to other mice that were genetically engineered to develop lung cancer showed that the presence of either ROCK1 or ROCK2 alone was sufficient to allow tumour cells to divide." (PMID 26950944, 2016). "Our hit list also comprised genes like ROCK1 and FAK that are known to play a role in migration, invasion and metastasis but have only recently been implicated in tumor progression." (PMID 27374095, 2016). "Cytoplasmic p21 was found to inhibit the activity of ROCK1, reduce the formation of actin stress fibers, and promote the invasion and metastasis of tumor cells." (PMID 26271467, 2015). "We focused on ROCK1 since there are increasing evidence that ROCK1 plays an important role in growth, survival and invasion of tumor cells and that it is also involved in the regulation of autophagy, apoptosis and differentiation." (PMID 25831237, 2015). "Evidently, downregulation of ROCK1 or ROCK2 constitutes a critical step in the tumor suppressor activity of miR-144." (PMID 25912304, 2015). "There was a significant positive correlation between central tumour and invasive front expression of ROCK1 (p <0.001)." (PMID 25380619, 2014). "In each pair of samples, ROCK1 levels were higher by qRT-PCR in normal tissue compared with the tumour samples (p = 0.016)." (PMID 25380619, 2014). "By IHC, 100% of invasive front areas of the tumour and 95.8% of central tumour areas were positive for ROCK1." (PMID 25380619, 2014). "When overexpressed, ROCK1 correlated inversely with lymph node metastasis in the central tumour and invasive front." (PMID 25380619, 2014). "Our results do not allow us to conclude much concerning the amplification of ROCK1 in the tumour samples or on the possible generation of aberrant mRNA or truncated protein." (PMID 25380619, 2014). "The actin cytoskeleton dynamics mechanism in tumor biology behavior, as the regulation of the actin cytoskeleton in cancer prevention and control in the sense Rac1, Pak1 and Rock1 is worth studying." (PMID 23298303, 2014). "By RT-qPCR, ROCK1 was overexpressed in normal adjacent samples compared with the tumour tissue (p = 0.0167)." (PMID 25380619, 2014). "ROCK1 expression levels were measured in 16 vulvar tumour samples and adjacent normal tissue by qRT-PCR." (PMID 25380619, 2014). "The precise function of ROCK1 in carcinogenesis and in the architectural rearrangement of tumour cells during metastasis remains debated." (PMID 25380619, 2014). "Western blot analysis showed that treatment of Ad-ANGPTL4 suppressed the expression of ROCK1 protein in tumor tissues compared to the control group." (PMID 25148701, 2014). "ROCK1 immunopositivity was observed in the tumour invasion fronts of all cases and in nearly all central tumour areas." (PMID 25380619, 2014). "ROCK1 is correlated with tumor migration and invasion and Rho/ROCK pathway participates in regulating cytoskeletal signalling." (PMID 24180482, 2013).
tumor (continued). "Increased expression of RhoA or RhoC GTPAses and/or their ROCK1/2 effectors has been reported in several metastatic cancers, and they play important roles in tumour progression and invasion." (PMID 22583596, 2012). "This work shows that amoeboid tumour cells migrate in stiff matrices by upregulating ROCK1 activity and cell contractility via an epigenetically-derived, Notch1-dependant mechanism." (PMID 22583596, 2012). "In conclusion, this is the first study to document that miR-1280 functions as a tumor suppressor by targeting oncogene ROCK1 to invasion/migration and metastasis." (PMID 23056431, 2012). "Rearranging cytoskeletal proteins is important for the ability of tumor cells to metastasize and our study showed that miR-1280 attenuated expression of oncogene ROCK1." (PMID 23056431, 2012). "Here, we are able to glimpse into how tumour cells are inherently plastic where cells can swap between migration modes utilising ROCK1 and/or MMPs." (PMID 22583596, 2012). "miR-584 is a new tumour suppressor miR in ccRCC and inhibits cell motility through downregulation of ROCK-1." (PMID 21119662, 2011). "In addition, GLIPR1 has been implicated in the regulation of epithelial–mesenchymal transition (EMT), cancer cell motility, and anti-tumor immune responses through pathways such as PI3K/PDK1/ROCK1." (PMID 41208460, 2025). "Furthermore, the use of the ROCK1 inhibitor Y-27632 enhances the phagocytic activity of macrophages and improves the sensitivity of tumor cells to hormone therapy." (PMID 40368918, 2025). "Pan-cancer analyses reveal ROCK1’s implication in tumor progression, suggesting potential epigenetic crosstalk between bone metabolism and the tumor microenvironment, while methodologically aligning with prior glutamine metabolic gene through shared LASSO and SVM-RFE algorithm." (PMID 41458498, 2025). "Additionally, ROCK1 acts as a mediator of the reciprocal interactions between tumor cells and their microenvironment." (PMID 40368918, 2025). "Co-inhibition of ATOX1 and ROCK1 either by siRNA transfection or inhibitory drugs could lead to a significant decrease in tumour proliferation." (PMID 40940984, 2025). "circFECR1 was also shown to promote tumor metastasis via the miR584-3p/ROCK1 pathway in SCLC cells." (PMID 41299506, 2025). "Interestingly, we observed that patients with high ROCK1 expression had elevated tumor purity, while those with low expression exhibited higher immune scores." (PMID 40368918, 2025). "Likewise, tumor-suppressive miR-199a/b inhibits ROCK1/MLC and PI3K/Akt pathways via targeting the Rho-associated coiled-coil kinase 1 (ROCK1) in HBV-HCC, and its low expression is also associated with poor overall survival." (PMID 40625740, 2025). "Existing research indicates that ROCK1 plays a pivotal role in facilitating tumor progression." (PMID 39503247, 2024). "Additionally, in glioma, miR-584-3p acts as a tumor suppressor impairing cell motility by regulating ROCK1." (PMID 39000555, 2024). "Ectopic expression of miR-340 suppressed ROCK1 by directly binding to its 3’-untranslated region, resulting in significant inhibition of cell proliferation, migration, and invasion in OS cell lines in vitro, and OS tumor growth in a mouse xenograft model." (PMID 37240338, 2023). "The relationship between ROCK1 and tumor prognosis in pan-cancer should be explored, which may help further understand the role of low-ROCK1 expression in PMOP patients’ cancer risk." (PMID 37683138, 2023). "All results indicated that regulating Linc00205 can interact with miR-154-3p and ROCK1 to help produce a massive impact on tumor progression and metastasis through the MAPK signaling pathway, EMT pathway, cell cycle-related pathway and apoptosis-related pathway." (PMID 35179516, 2022).
tumor (continued). "However, fasudil has low potency in inhibiting ROCK1, and its activity of inhibiting tumor cell growth in vitro is at the micromolar level, which is too high to achieve in vivo effect." (PMID 36561342, 2022). "The proteomic analysis of tumor tissues identified that rho-associated coiled-coil containing protein kinase 1 (ROCK1), transgelin 2 (TAGLN2), and FCH and Mu domain containing endocytic adaptor 2 (FCHO2) levels were significantly reduced in chrysin-treated tumor tissues." (PMID 36077069, 2022). "In addition, it was shown that miR186 targets ROCK-1 (Rho-associated protein kinase 1) and IGF1 (Insulin-like growth factor 1) in tumor cells." (PMID 35444657, 2022). "Results from the ROCK1nc mouse model indicate that blocking caspase-induced ROCK1 activation leads to increased acute inflammation that results in greater innate and adaptive immune responses, which were correlated with reduced tumour numbers." (PMID 36497425, 2022). "Other targets of miR-199a that may affect tumor proliferation and metastasis are ROCK1, HIF1α, BCAM, FZD6, and DDR1." (PMID 36499729, 2022). "In addition, perturbation of the chemokine GPCR, CXCR4, signaling promotes BC cell migration by regulating tumor cell adhesion events through provision of an optimal level of ROCK1 activity for effective cell migration." (PMID 33053607, 2022). "Interestingly, Arf6 works with RhoA, the main activator of ROCK1, to generate tumor-derived microvesicles, suggesting a potential role for the R-Ras family in this process." (PMID 34530870, 2021). "Also, the data from TCGA database showed that ROCK1 expression was elevated in PC tumor tissues and that ROCK1 overexpression was significantly correlated with poor prognosis." (PMID 33414429, 2021). "Our previous study also found that miR-124-3p could function as a tumor suppressor in OS by targeting ROCK1." (PMID 34373692, 2021). "Additionally, the expression of SNHG20 and ROCK1 was remarkably suppressed, but the expression of miR-148a was strikingly increased in the tumor tissues from sh-SNHG20 group." (PMID 34836544, 2021). "This study revealed a role for caspase activation of ROCK1 in liver homeostasis when challenged with a strong apoptotic stimulus and a previously unknown role for sterile inflammation as a mechanism of tumour suppression." (PMID 33871359, 2021). "As Rho family of GTPases are key player in lymphocyte development and activation, and cancer cell exploiting one of their family member (ROCK1) to escape immune activity is similar to hijacking of macrophage‐produced complement C1q to promote their own tumor growth." (PMID 33587338, 2021). "We, therefore, next explored whether ROCK1/2-Myosin II sustains tumour initiation via regulation of Wnt ligands and independently of other functions." (PMID 33082334, 2020). "We first explored whether ROCK1/2-Myosin II sustains in vitro tumour initiation by blocking the entire transcriptional programme using different ROCKi (H1152 and GSK269962A)." (PMID 33082334, 2020). "Therefore, the disordered Rho/ROCK1 signaling pathway can easily lead to tumor development and progression." (PMID 33168781, 2020). "Besides, the ROCK1 expression in each tumor was examined by immunohistochemistry staining, immunoblot, and RT-PCR analysis, respectively." (PMID 32219065, 2020). "However, simultaneous suppression of ROCK1 dramatically slowed down the tumor growth rate despite of LINC00452 overexpression." (PMID 33168781, 2020). "Up-regulated TUG1 contributes to tumor growth in laryngocarcinoma via miR-145-5p/ROCK1 pathway." (PMID 33061856, 2020). "Similarly, the decreased miR-139 in OS was also been identified as a suppressor in tumorigenesis, and its suppressive effects on tumor cell proliferation and invasion were exerted by targeting ROCK1." (PMID 31651329, 2019). "So far the well-established role of ROCK1 supported a positive function in tumor growth." (PMID 31638991, 2019).